IL10 (interleukin 10)
Diseases named in the same sentence as IL10 in open-access papers (continued):
Sharing a sentence is not in itself a finding about the gene and the disease.
malaria (continued). "The frequency of Tr1 cells that expressed IL-10, IFNγ, and PD-1 increased in both symptomatic malaria and asymptomatic parasitemia." (PMID 41000872, 2025). "Together, these findings highlight the central role of IL-10 in orchestrating both systemic and cellular immune regulation during chronic malaria exposure in chimpanzees." (PMID 41279035, 2025). "In line with our previous work showing that human NK cells secrete minimal IL-10 with IL-15 treatment alone, we observed that less than 1% of malaria-naive and malaria-experienced NK cells release IL-10 under these conditions." (PMID 40337867, 2025). "While not observed in this mouse model, additional cytokines including IFN-γ, TNF-α, and IL-10 have been reported in the placenta of malaria-infected pregnant women." (PMID 40470930, 2025). "Here we show that in naive populations, monocytes from children also produce more IL10 compared to adults, in an age-intrinsic manner, distinct from malaria-induced regulator networks." (PMID 41027884, 2025). "TNF-α elevation has been previously associated with anemia and high-density P. falciparum infection, whereas reduced IL-10 demonstrated in African children with severe malaria-induced anemia." (PMID 40014608, 2025). "Studies in mice and humans demonstrate that enhanced production of IL-10 typically accompanies both acute and chronic Plasmodium infection, suggesting that this cytokine modulates the degree of inflammation in malaria." (PMID 40972121, 2025). "Our data demonstrate that CXCR6+ CD127− Tr1 dominate the response to Pf infected red blood cell antigens, rapidly expand following malaria in vivo, and express IL-10 and IFNγ in vivo during both symptomatic malaria and asymptomatic parasitemia." (PMID 41000872, 2025). "In our study, the mean concentration of IL-10 was significantly higher in patients with malaria only, 293.12 (±106.80), compared to those with comorbidity, 255.30 (±176.95) and healthy controls 130.93 (±51.56)." (PMID 40014608, 2025). "Children with severe malarial anemia had higher plasma levels of TNF‐α (p < .001), IFN‐ɣ (p < .001), IL‐1β (p < .001), IL‐6 (p < .001), GM‐CSF (p < .001), and IL‐10 (p < .001) than those with malaria only, and mild/moderate anemia." (PMID 39240033, 2024). "On the other hand, the mean level of IL-10 is higher in uncomplicated than complicated malaria (105.73 ± 32.06pg/ml vs. 40.60 ± 9.11pg/ml, p < 0.001)." (PMID 39039450, 2024). "Inhibiting IFN-γ and increasing IL-10, an attempt to balance anti-inflammatory and pro-inflammatory cytokines, seem fundamental to controlling parasitemia, symptoms, and severity of malaria." (PMID 39703398, 2024). "On the contrary, the results of Mbengue, Niang show that IL-10 levels are the same in both asymptomatic and severe malaria." (PMID 38404582, 2024). "The pathophysiological mechanism of pain and other symptoms can involve the release of inflammatory cytokines, especially TNF-α, IL-1, IL-6, IFN-γ, IL-8, IL-10, and IL-13, during the inflammatory response induced by malaria." (PMID 38774541, 2024). "Participants with malaria had higher TNF‐α/IL‐10, TNF‐α/TGF‐β, IFN‐ɣ/TGF‐β, IL‐1β/TGF‐β and, but lower IFN‐ɣ/IL‐10, IL‐1β/IL‐10, and IL‐6/TGF‐β ratios than those in the control group." (PMID 39240033, 2024). "The intense sequestration exacerbates the inflammatory response and cause cytokine storm, especially increasing IL‐10, GM‐CSF, IL‐6, IL‐1β, IFN‐ɣ, and TNF‐α levels, which promotes the progression of severe malaria." (PMID 39240033, 2024). "On the contrary, TNF‐α/IL‐10 and IL‐6/IL‐10 ratios were reduced when malaria‐infected children were compared with uninfected group in Malawi." (PMID 39240033, 2024). "A proportional increase in TGF-β and TNF-a, IL-10, and IL-1β, predicts a proportional increase in severe forms of malaria, especially in CM patients." (PMID 38404582, 2024).
malaria (continued). "In the present study, children with severe malarial anemia had significantly elevated plasma levels of TNF‐α, IFN‐ɣ, IL‐1β, IL‐6, GM‐CSF and IL‐10 than those with uncomplicated malaria, and this is in consonance with earlier findings." (PMID 39240033, 2024). "Other cytokines such as IL-4, IL-6, and IL-10 were also elevated in coinfections compared to malaria monoinfection." (PMID 36716305, 2023). "Another review suggested that IL-10 along with other immunoregulatory cytokines mediate the development of immunity against malaria, but the full impact of the production of IL-10 during malaria infection is still unclear." (PMID 36668942, 2023). "IL-10 can regulate the neutrophil function by the upregulation of the IL-1Ra and can limit the disease severity in patients with uncomplicated malaria." (PMID 36668942, 2023). "The high levels of IL-10 in patients with severe malaria indicate the imbalance of this cytokine in the pathogenesis of severe malaria." (PMID 36668942, 2023). "Similar to the IL-10 levels, the IL-6 levels were seen to be higher in children with severe malaria cases than those with uncomplicated malaria." (PMID 36668942, 2023). "IL-10 is a cytokine involved in immunopathology and protection during malaria, reducing the inflammatory response." (PMID 37628675, 2023). "Given that immune response cells produce cytokines and malaria severity is associated with elevated concentrations of TNF-α, IL-6 and IL-10." (PMID 37628731, 2023). "Data showed there was significant increase in IL-10 production in B cells during malaria, indicating of malaria induction of Bregs." (PMID 37968278, 2023). "Again, distinct IL-10 levels were frequently observed among schistosomiasis coinfections compared to malaria monoinfection." (PMID 36716305, 2023). "Distinct cytokine profiles in malaria and filariasis coinfections were IL-1Ra, IL-10, CXCL5, CXCL8, and CXCL10." (PMID 36716305, 2023). "Increased IL-10 levels were observed in children with severe or moderate anemia than in those with uncomplicated malaria." (PMID 36668942, 2023). "Within the CD4 T cell compartment, type 1 regulatory (Tr1) cells that co-produce IFNγ and IL-10 during malaria, dominate antigen-specific CD4 T cell responses in children in high endemic areas." (PMID 37968278, 2023). "It has been shown in mice that the absence of IL-10 expression was associated with the development of severe malaria and excess mortality, suggesting a protective role, whereas high plasma IL-10 levels in humans were correlated with malaria severity and death." (PMID 36759905, 2023). "Another study in Malawian children found that the IL-10 levels were elevated in patients with cerebral malaria, severe anemia, and in those with uncomplicated malaria, which indicates higher-than-normal levels of this cytokine." (PMID 36668942, 2023). "Nevertheless, both IL-10 and IL-6 have been reported to be lower in severe anemia compared with uncomplicated malaria, which indicates the dual role of IL-6 and IL-10 in anti-inflammatory processes." (PMID 36668942, 2023). "We confirmed that malaria-specific IL-10/IFNγ co-producing cells also produce IL-21 using a flow cytometric assay." (PMID 37634385, 2023). "Nevertheless, the IL-10 levels in patients with malaria were reported to be lower or similar in different studies." (PMID 36668942, 2023). "The significantly higher levels of IL-6 and IL-10 observed in severe malarial anemia than in uncomplicated malaria suggest that these cytokines are induced during P. falciparum malarial anemia and play a role in the pathophysiology." (PMID 36787308, 2023). "Although the overall meta-analysis results indicated that IL-10 can be a potential marker for severe malaria, the sensitivity analysis demonstrated outliers that affect the robustness of the results of the meta-analysis." (PMID 36668942, 2023).
malaria (continued). "Compared with healthy individuals, the IL-10 levels in patients with malaria were reported to be higher and correlated with an increased parasite density." (PMID 36668942, 2023). "Our results are in line with most human studies suggesting a role for high plasma IL-10 in malaria severity and CM death." (PMID 36759905, 2023). "FGA is a structural component of the extracellular matrix, while ALB is involved in oxygen binding; IL10 in African trypanosomiasis signaling and the malaria signaling pathway, and REN in the renin angiotensin system signaling pathway." (PMID 36762194, 2023). "In this study, we identified a molecular signature that distinguished human IL-10–Th1 cells from IL-10+Tr1 cells in malaria — a parasitic disease with high morbidity, yet unmet medical needs." (PMID 36594463, 2023). "Another study suggested that the production of IL-10 was impaired in severe malaria compared with uncomplicated malaria." (PMID 36668942, 2023). "Consistent with this, we show significantly increased ex vivo secretion of IL-10 from B cells during malaria compared with 28 days post-treatment in additional individuals." (PMID 37968278, 2023). "Primigravid women had higher percentages of malaria-specific, nnCD4+ T cells that co-express IL-10 and IFNγ compared with multigravid women." (PMID 37634385, 2023). "Interleukin-5, IL-1α, and IL-10 were significantly higher in malaria seropositive than seronegative volunteers." (PMID 38274822, 2023). "In the different severity of clinical malaria, such as severe anemia and cerebral malaria, the IL-10 levels were much lower in severe anemia compared to cerebral malaria." (PMID 36668942, 2023). "cMaf was also reported to be important for the induction of CD4+ T cell-produced IL-10, which is required to suppress Th1-, Th2-, and Th17-mediated pathology in experimental models of malaria, allergy, and autoimmunity, respectively." (PMID 36594463, 2023). "IL-10 displays a protective role in the tissue from infection-mediated inflammation during infection, preventing severe malaria symptoms, such as anemia and organ damage." (PMID 37628675, 2023). "Through this analysis, we identified a population of activated, malaria-specific, interleukin-10 (IL-10) and interferon-gamma (IFNγ) expressing CD4+ T cells that were more common in primigravid versus multigravid women." (PMID 37634385, 2023). "The next common cytokine that studies evaluated in both malaria and other parasite coinfections was IL-10." (PMID 36716305, 2023). "Control of intracellular parasites responsible for malaria requires host IFN-γ+T-bet+CD4+ T cells (Th1 cells) with IL-10 produced by Th1 cells to mitigate the pathology induced by this inflammatory response." (PMID 36594463, 2023). "Another study showed significantly elevated IL-6 and IL-10 levels in children with severe malaria compared with uncomplicated malaria." (PMID 36668942, 2023). "Co-infection of BALB/c mice with L. amazonensis and P. yoelii or L. braziliensis and P. yoelii reduced serum levels of the cytokines IFN-γ, TNF-α, IL-6 and IL-10 induced by the malaria parasite." (PMID 36895563, 2023). "Given the importance of the pro-and anti-inflammatory balance during malaria, a comparison was performed between the ratio of the main pro-inflammatory (IL-6 and TNF-α) and anti-inflammatory (IL-10) cytokines identified in the malaria and coinfected groups." (PMID 35749690, 2022). "The IL-10/tumor necrosis factor–α ratio was also lower in patients with co-infections (10-fold) compared with those who had malaria monoinfection (30-fold)." (PMID 36269701, 2022). "In endemic settings, the frequency of IL-10-producing CD4+ T cells correlated with the number of malaria exposures." (PMID 36389662, 2022). "In this analysis, the coinfected group had a higher level of IL-10 than the inflammatory cytokines, compared to the profile seen in the malaria group." (PMID 35749690, 2022).
malaria (continued). "The increased IL-10 concentration in patients with severe malaria can be explained as a response to the elevated levels of pro-inflammatory cytokines." (PMID 36178979, 2022). "Elevated IL-10 levels have been observed in patients with Plasmodium-schistosomiasis and malaria-hookworm co-infection." (PMID 35421083, 2022). "The immunosuppressive cytokine IL-10 (which also stimulates antibody (IgA) production) can prevent immunopathology during malaria." (PMID 35632518, 2022). "The IL-10/IL-6 ratio tended to be higher in patients with co-infections (twofold) compared with malaria monoinfection." (PMID 36269701, 2022). "The role of IL-10 cytokine as an immunoregulator is well recognised in malaria pathogenesis by counteracting the effects of the proinflammatory cytokines mainly produced by Th1 cells." (PMID 35277125, 2022). "Together, these results from mouse models of malaria suggest that IL-10 is needed to protect from excessive tissue inflammation, but thereby also promotes parasite proliferation." (PMID 35464430, 2022). "IL-6, IL-13, TNF-α, and IFN-γ were significantly higher in severe malaria, while IL-7, IL-10, IL-17, and IL-27 showed the opposite trend." (PMID 36293524, 2022). "An imbalance of cytokines such as tumor necrosis factor (TNF), interleukin-6 (IL-6), IL-10, and interferon-gamma (IFN-γ) are implicated in malaria related-inflammation that induce changes in iron absorption and delocalization." (PMID 36183114, 2022). "Previously, researchers discovered that TNF and Th2 group cytokines, such as IL-6 and IL-10 concentrations, were elevated in individuals with severe malaria, indicating that these cytokines play a role in the etiology of malaria disease severity." (PMID 35820892, 2022). "As expected, in malaria patients, parasitemia was positively correlated with the anti and pro-inflammatory cytokines IL-10 and TNF-α." (PMID 35749690, 2022). "Between them, TNF-α, interleukin 10 (IL-10) and IL-6 are molecules that can be a powerful inflammatory marker of severity during malaria." (PMID 35749690, 2022). "We also analysed IL-10 inducing epitopes in murine malaria parasites namely P. berghei and P. yoelii." (PMID 35277125, 2022). "In mouse models of liver-stage malaria, there is a distinct increase in IL-4, IL-10, TGF-β, and downregulation of IFN-γ, IL-12, and TNFα." (PMID 36415655, 2022). "As expected, the IL-10/IL-6 ratio was lower in malaria group when compared to the coinfected, showing that in the coinfected the response was leaning more towards a suppressive profile." (PMID 35749690, 2022). "Ablation of IL-10 resulted in minimal worm clearance and fatal tissue damage in T. gondii, malaria, and Trypanosoma cruzi-infected models." (PMID 36310865, 2022). "Several studies using different mouse models of malaria indicate that IL-10 is accountable for the dynamic growth of parasites and also associated with disease pathogenesis." (PMID 35109868, 2022). "IL-10 plays a critical role in the immunoregulatory networks and protects tissue from infection-induced inflammation during malaria pathology." (PMID 33562617, 2021). "The ratio between IL-10 levels and parasite density was 0.008 and 0.01 for clinical and asymptomatic malaria respectively, whereas for IL-6 the ratio was 0.0014 versus 0.00088, and for TNF-α 0.0014 versus 0.010." (PMID 34177883, 2021). "There has been convincing mechanistic evidence from preclinical malaria models and patient data showing key roles for IL-10 in preventing several severe manifestations of malaria including development of anemia and damage to organs." (PMID 33562617, 2021). "The malaria drugs chloroquine and artemisinin reduced the haemozoin-induced M2 phenotype by reducing IL-10 and CD206." (PMID 33330947, 2021). "In the present study, we found that healthy controls had very low IL-10 levels, whereas Malaria cases had significant higher levels of IL-10." (PMID 34962938, 2021).
malaria (continued). "Investigations in children infected with malaria showed increased levels of arginase 1 and IL-10, reduced amounts of NO, and increased expression of M2 markers (CD163, CD206)." (PMID 33330947, 2021). "IL-10 concentrations were also higher in asymptomatic participants and exhibited a positive correlation with the time living in endemic area, when all malaria cases were included in the analysis." (PMID 34727121, 2021). "Patients with symptoms had the highest MDP levels, except for IL-10 and indirect bilirubin, which were higher in the asymptomatic malaria group." (PMID 34727121, 2021). "Cytokine concentrations correlated positively with malaria parasite density with the strongest correlation for IL-10 in both asymptomatic (r=0.63) and clinical malaria (r=0.53)." (PMID 34177883, 2021). "In contrast, anti-inflammatory immunomodulators, TGFβ, and IL-10 were considered important in reducing inflammation and pathology during malaria." (PMID 34414129, 2021). "These together with the significant changes in the cytokine levels (IL-6 and IL-10) point to the debilitating effect of malaria on the immune system." (PMID 35223394, 2021). "A recent study found a correlation between P. falciparum-specific IL-10-positive T cells (IFN-γ- TNF-) and the risk of clinical malaria once infected." (PMID 34790829, 2021). "Together, these findings reinforce the premise that an immune suppressive environment against malaria developed for children diagnosed with eBL, and that their IL-10 production by T cells was elevated against both EBNA1 and PfSEA-1A." (PMID 34771539, 2021). "We found a significant positive relation between parasite densities and circulating cytokine levels (IL-10), both in asymptomatic and clinical malaria cases." (PMID 34177883, 2021). "Asymptomatic malaria is characterized by increased Treg numbers, IL-10 and TGF-β production, and dampened TNF, IFN-γ pro-inflammatory response characterizes." (PMID 33746974, 2021). "Our studies of the temporal features, spatial relationships, critical cellular sources and mechanisms by which IL-10 promotes humoral immunity during malaria highlight the distinct mechanisms governing anti-malarial immunity." (PMID 33529242, 2021). "Similar to asymptomatically infected adults, plasma IL-10 levels exhibited the largest increase with a 150-fold increase during acute malaria compared to baseline." (PMID 33407502, 2021). "IL-10 is an anti-inflammatory cytokine that down-regulates IFN-γ and has been associated with immune suppression during severe malaria in children." (PMID 34771539, 2021). "IL-10 is a pleiotropic cytokine expressed during malaria and is essential for anti-Plasmodium humoral immunity." (PMID 34414129, 2021). "Here, we characterized EBNA1-specific IFN-γ, IL-10 and IL-17A T cell responses in eBL children compared to healthy children residing in malaria holoendemic (Kisumu) and hypoendemic (Nandi) regions of Kenya to gain further insights into eBL immunopathology." (PMID 34771539, 2021). "The largest difference was found for IL-10, confirming the presence and importance of an anti-inflammatory response in asymptomatic malaria to dampen the pro-inflammatory response and prevent the development of clinical disease." (PMID 34177883, 2021). "Taken together, these data indicate that IL-10 plays a prominent role in the cytokine response to P. falciparum in malaria-endemic settings." (PMID 33407502, 2021). "TNF-α and IL-10 levels were increased in Malaria cases versus controls, but IFN-γ and TGF- β levels were comparable between the groups." (PMID 34962938, 2021). "Reporter mice for IL-10 (eGFP) and FOXP3 (RFP) were infected by intraperitoneal injection of 1 × 105Plasmodium berghei ANKA parasites, one of the causative agents of malaria in mice." (PMID 34910301, 2021).